ST6GAL1 (ST6 beta-galactoside alpha-2,6-sialyltransferase 1)
Diseases named in the same sentence as ST6GAL1 in open-access papers (continued):
Sharing a sentence is not in itself a finding about the gene and the disease.
cancer (continued). "ST6GAL1 is overexpressed in numerous cancer types, and there is extensive literature linking ST6GAL1 to tumour grade, metastasis and poor patient prognosis." (PMID 36077781, 2022). "In a study of HCC probing immune escape of cancer cells via modulation of T cell function, cells exhibiting upregulated ST6Gal1 were co-cultured with cytotoxic CD8+ T-cells resulting in increased secretion of TGF-β1 by the T-cells." (PMID 36106023, 2022). "Lastly, there is also the intriguing possibility that cancer cell natively expressed ST6GAL1 needs to be first excreted into the extracellular space." (PMID 35676533, 2022). "To date, ST6GAL1 is known to exert its biological effects in cancer cells by modulating the function of select receptors including TNF Receptor 1 (TNFR1) and EGFR, leading to the activation of transcription factors such as NF-κB." (PMID 36345944, 2022). "Early work suggested that circulating ST6GAL1 is mainly released by the liver, but recent studies suggest that cancer cells also have the capacity to increase extracellular ST6GAL1 levels." (PMID 36077781, 2022). "Overexpression of the enzyme ST6GAL1 and its glycan product, sTn, leads to an increased migration and invasion in carcinoma." (PMID 35744954, 2022). "EGFR, another cancer-associated member of the ErbB RTK receptor family, was found to be significantly less activated in ST6GAL1 K.O. cells, upon treatment with trastuzumab." (PMID 33947960, 2021). "In the ST6GAL family, ST6GAL1 is ubiquitously expressed and is the most investigated ST in cancer, while ST6GAL2 is mainly expressed in the brain." (PMID 33921986, 2021). "ST6Gal1 is frequently overexpressed in many solid tumors, such as pancreatic, gastric, cervical, ovarian, brain and colorectal cancers and cancer cell lines." (PMID 34975914, 2021). "ST6GALNAC1 induces stem-like cell properties via activation of AKT pathway, while ST6GAL1 has been evidenced to induce the expression of stem cell transcription factors Sox9 and Slug, thereby promoting cancer cell stemness." (PMID 34070747, 2021). "Recently, molecular analysis has confirmed that ST6GAL1 decreases the sensitization of cancer cells to trastuzumab-induced cytotoxicity through directly enhancing α2,6-sialylation of ErbB2, which results in the increased activation of both ErbB2 and EGFR RTKs." (PMID 34745942, 2021). "Herein, we used a strategic systems-based approach integrating glycomics of the KC mouse, modeling early events in transformation, with human data to identify ST6GAL1 (e.g., α-2,6-sialic acid) as a potential cancer promoter." (PMID 34634466, 2021). "ST6GAL1 has been shown to promote a more migratory and invasive phenotype in several types of cancer." (PMID 33921986, 2021). "Overall, the herein described molecular mechanism further corroborates the previously reported oncogenic role of ST6Gal1 in other human cancer models." (PMID 33947960, 2021). "Surprisingly, enzymes responsible for the biosynthesis of well-known cancer-associated structures, such as β1,6 branching (MGAT5), sialyl-Tn (ST6GALNAC1) sLex (FUT6), Sia6LacNAc (ST6GAL1), and core-fucosylation (FUT8) lack any relationship with survival." (PMID 33919332, 2021). "ST6GAL1 endows resistance of cancer cells to gefitinib (EGFR inhibitor) and trastuzumab (anti-ErbB2 antibody) and also confers tumor cell resistance against hypoxia via enhancing hypoxia-inducible factor-1α (HIF-1α) expression." (PMID 34745942, 2021). "It is clear from the presented literature that ST3GAL1 and ST6GAL1 are the most extensively studied sialyltransferases in cancer." (PMID 33921986, 2021). "ST6GAL1 has also been documented for its role in other cancer cellular processes including angiogenesis, inflammation, and apoptotic resistance." (PMID 34290711, 2021). "Our deletion of ST6GAL1 in only pancreatic-specific lineages in the KC mouse (ST6KC) enabled the assessment of the ductal intrinsic impact of ST6GAL1 in promoting cancer formation and progression." (PMID 34634466, 2021).
cancer (continued). "High expression of ST6GAL1 in cancer correlates with worse tumor grade, advanced stage of disease, and poor prognosis." (PMID 34975914, 2021). "The expression of ST6GAL1 has been determined to be downregulated in some cancers including bladder cancer and upregulated in others such as prostate, lung, and breast cancer." (PMID 34290711, 2021). "First, both the SOX2 and ST6GAL1 genes are extensively amplified, but rarely deleted, across multiple cancer types." (PMID 31610800, 2019). "The sialyltransferase ST6GAL1 has been reported to be upregulated in various cancers, contributing to increase tumor aggressiveness, metastasis and enhance cancer cells’ resistance to chemotherapy." (PMID 30478534, 2019). "At the very least, the ability of cancer-derived ST6GAL1 to disrupt granulopoiesis predicts a diminished capacity for the patient to combat bacterial infections." (PMID 31408003, 2019). "Key examples of sialyltransferases important in cancer include ST6GAL1; ST3GAL4 ST3GAL6 and ST6GalNAc1/2." (PMID 31614918, 2019). "This current work is the first to examine how cancer-derived ST6GAL1 can perturb the generation of granulocytes, the best documented biologic role associated with extrinsic ST6GAL1 sialylation." (PMID 31408003, 2019). "In epithelial carcinomas, ST6GAL1 expression confers increased resistance to chemotherapy, hypoxia, and nutrient deprivation by promoting a stem-like phenotype, bolstering signaling through pro-survival and pro-proliferative EGFR, HIF-1α, and NF-κB pathways." (PMID 31408003, 2019). "Although inhibition of ST6Gal1 expression has been reported to increase tumor cell proliferation and tumor growth in vitro and in vivo, our studies showed that NDAT decreased ST6Gal1 expression and cancer cell proliferation." (PMID 30187356, 2018). "ST6Gal-1-dependent sialylation of the TNF-α receptor has been shown to enhance pro-survival signaling in cancer cells." (PMID 30294329, 2018). "ST6Gal1 is normally expressed in all homeostatic tissue but has been shown to be up-regulated in a variety of cancer tissues, including colon and breast, to name a few." (PMID 29912148, 2018). "The results support our finding in animal studies that ST6Gal1 mediates the promoting effect of fructose on cancer metastasis." (PMID 28032597, 2017). "ST6GAl1 is important for controlling sialylation of N-terminal glycans, and is over-expressed in many types of cancer." (PMID 27428423, 2016). "All these genes have already been associated with hypermutated regions in BCLs (BCL2, BCL6, BCL7A, BIRC3, CIITA and ST6GAL1) or listed in the Cancer Gene Census (BCL2, BCL6, BCL7A, BIRC3, CIITA, IGLL5 – in the IGL@ locus – and LPP)." (PMID 25903198, 2015). "Accumulating evidence shows that ST6GAL1 is aberrantly expressed in various cancer entities such as colon, breast, and epithelial tumor types, and most studies propose an oncogenic role for ST6GAL1." (PMID 25465919, 2014). "Our study using patient plasma supports this hypothesis; in sEVs from patients with more aggressive cancers, only the ST6GAL1 membrane-bound form is detected while both forms are expressed in sEVs from patients with less aggressive cancers." (PMID 40938891, 2025). "This study could bring light into the widely described tumorigenic role of ST6GAL1 in many cancer cell types, including PrCa, as it contributes to tumor growth and invasion while it is expressed at low levels in the epithelium of normal tissues." (PMID 40938891, 2025). "Moreover, we notified that two kinds of PD‐i1+ T cells were found within the adjacent spots near ST6GAL1‐low cancer cells." (PMID 40847469, 2025). "Notably, the removal of sialylation completely blocked the protumor activity of ST6GAL1, underscoring the importance of sialylation in cancer cells." (PMID 39937175, 2025). "Notably, high ST6GAL1 expression and increased sialylation have been reported in various cancer types, including pancreatic, colorectal, prostate, breast, and ovarian cancers." (PMID 39937175, 2025).
cancer (continued). "We propose that ST6GAL1 may be released by cancer cells in small extracellular vesicles (sEVs) in the PrCa tumor microenvironment to potentially modulate cell surface sialylation in recipient cells." (PMID 40938891, 2025). "ST6GAL1 expression is low in normal tissue but increases in many cancer cell types." (PMID 40938891, 2025). "Additionally, sialylation of tumor necrosis factor receptor 1, Fas (CD95), and galectin-3 by ST6GAL1 provides protection against apoptosis in cancer cells." (PMID 39937175, 2025). "In view of these findings, we have focused our work on the discovery of a cell-permeable and selective small molecule inhibitor of ST6GAL1 for use as an experimental tool compound and as a lead for the further development of a preclinical cancer drug candidate." (PMID 38673867, 2024). "ST6GAL1 endows cancer cells with stemness features including tumor-initiating potential in limiting dilution assays; we therefore postulated ST6GAL1 may facilitate early stages in PDAC development." (PMID 37643018, 2023). "However, EVs containing ST6Gal1 potentiate aggressive cancer cell growth, proliferation, and invasion in cells containing low amounts of endogenous ST6Gal1." (PMID 37629204, 2023). "Extensive studies were performed to find that ST6GAL1 was related to cancers." (PMID 37761904, 2023). "ST6GAL1 also confers cancer stem cell (CSC) characteristics, which may be due, in part, to its activity in upregulating the expression of transcription factors such as SRY-box transcription factor 9 (SOX9)." (PMID 37643018, 2023). "Therefore, ST6Gal-1 is considered a biomarker of ionizing radiation and related therapeutic resistance in various cancers." (PMID 37894470, 2023). "In the same cancer model, ST6Gal1 activated β1-integrin, further enhancing attachment to collagen and laminin: this resulted in heightened motility and highlighted the importance of ST6Gal1-regulated β1 integrin in disease progression and migration." (PMID 36106023, 2022). "Considering the importance of amplifications of EGFR in cancer, this mechanism of ST6Gal1 action may also contribute to oncogenesis and/or tumor progression." (PMID 36106023, 2022). "Pathways and targets affected by ST6Gal1 to impact cancer hallmarks." (PMID 36106023, 2022). "Using KM plotter web-based data analysis, our results suggested that tumor ST6GAL1 mRNA was associated with favorable disease-free survival of TNBC patients, suggesting a complex mechanism of ST6GAL1-mediated cancer progression, warrant further investigation involving tumor microenvironment (TME)." (PMID 35676533, 2022). "However, a few reports correlated better long-term patient survival among individuals with the most aggressive cancers and the highest cancer ST6GAL1." (PMID 35676533, 2022). "ST6Gal1 is the most intensively studied sialyltransferase in cancer." (PMID 35371997, 2022). "The mouse 4T1.2, the human MDA-231, and BT-549 cells that form invadopodia in an in vitro 3D culture setting were used to assess how extracellular ST6GAL1 might affect aggressive cancer cell’s invasiveness." (PMID 35676533, 2022). "Since α-2,6-sialilation is often correlated with increased tumor invasiveness, the transfer of ST6Gal1 and other glycosylation-related enzymes may be yet another mechanism by which EVs promote cancer progression." (PMID 36430846, 2022). "However, the immunomodulatory impacts of ST6Gal1 in general and in the context of cancer remain to be further explored: the importance of these studies will only increase with expanded use of immunotherapies." (PMID 36106023, 2022). "In addition, ST6GAL1 can modulate T-cell responses in the tumour microenvironment and play a role in cancer cell immune evasion." (PMID 36077781, 2022). "This elevation of ST6Gal1 in cancers is often attributed to gene amplification." (PMID 36106023, 2022).
cancer (continued). "Furthermore, alterations in Orai1 glycosylation have been observed in cancer cells and overexpression of the enzyme β-galactoside α-2,6-sialyltransferase 1 (ST6GAL1) has been reported to play a relevant role in cancer invasiveness and metastasis." (PMID 36612199, 2022). "Modulation of cancer stem cell maintenance by the Wnt pathway is well recognized, as is the promotion of stem cell maintenance by ST6Gal1 in myriad of neoplasms." (PMID 36106023, 2022). "Further, the altered expression of ST6GAL1 has been detected in many types of cancers." (PMID 35704638, 2022). "Furthermore, ST6GAL1-mediated α2,6-linked sialylation has been implicated in activating PI3K/AKT, epidermal growth factor receptor (EGFR) in some cancers, and cell growth and proliferation." (PMID 35676533, 2022). "Thus, signaling of the TNF superfamily in cancer is often modulated by ST6Gal1-mediated sialylation to avoid cell death and thereby promote tumor growth." (PMID 36106023, 2022). "While our data suggest the role of ST6GAL1 in driving aggressive cancer cell behavior, our data also indicate that the intrinsic ability of individual cancer cells to cell-autonomously express ST6GAL1 might not be absolutely necessary." (PMID 35676533, 2022). "Given the evidence of differential regulation of the Wnt pathway in ST6Gal1-modulated systems, and the importance of both Wnt and ST6Gal1 in cancer stem cell maintenance, it is imperative to understand the upstream and downstream mechanisms though which this signaling axis acts." (PMID 36106023, 2022). "ST6GAL1 plays an important role in cancer progression and metastasis." (PMID 34290711, 2021). "Several investigators observed that α2-6 sialylation by ST6Gal1 activity may protect cells from cell death, and eventually block homeostatic epithelial cell apoptosis in cancer." (PMID 34975914, 2021). "ST6Gal1 marked overexpression in multiple human cancers (including gastric), and the concomitant upregulation of α2,6-sialylation in specific target proteins, have been extensively associated with increased tumor invasive and metastatic capacities, as well as poor patient clinical outcome." (PMID 33947960, 2021). "Moreover, ST6GAL1 endows resistance of cancer cells to gefitinib (EGFR inhibitor) and trastuzumab (anti-ErbB2 antibody) and also predicts the sensitivity of lenvatinib treatment to patients with hepatocellular carcinoma." (PMID 34745942, 2021). "A pancreas-specific ST6GAL1 KO in the KC mouse delayed cancer formation and reduced fibrosis." (PMID 34634466, 2021). "Furthermore, sialylation of β1 integrins by ST6Gal1 conferred protection against galectin-3-induced apoptosis in a cancer cell line." (PMID 34975914, 2021). "•Pancreas-specific ST6GAL1 KO in KC mouse delays cancer formation." (PMID 34634466, 2021). "Likewise, there is a strong correspondence between SOX2 and ST6GAL1 CNGs in the NCI-60 panel of established cancer cell lines." (PMID 31610800, 2019). "Although reports of overexpression of human ST6GAL1 in cancer are common, we are not aware of any record of these specific mutations in ST6GAL1." (PMID 30775162, 2019). "However, ST6Gal-1-mediated attachment of α2,6-sialic acids on β1 integrin alters cellular adhesiveness leading to altered cell motility, cancer cell differentiation and progression." (PMID 30778346, 2019). "Collectively, our data hint at biologic effects of ST6GAL1 in cancer that extend beyond the cell-intrinsic modulation of oncogenic signaling pathways, instead being mediated by a novel, extrinsic axis of glycosylation, and galvanized by the growing importance of immune cells in malignancy." (PMID 31408003, 2019). "Furthermore, it is thought that ST6Gal1 is involved in maintaining stem cell-like behavior within the cancer tissue, allowing transformed cells to evade multiple apoptosis pathways." (PMID 29912148, 2018).
cancer (continued). "Accumulating evidence shows that ST6GAL1, an enzyme that catalyzes the transfer of sialic acid onto galactose-containing substrates, is aberrantly expressed in various cancers and may affect cell motility and invasion." (PMID 25465919, 2014). "Thus, there are multiple mechanisms through which ST6GAL1 could impact the immuno-landscape of cancers including GBMs." (PMID 36345944, 2022). "This conundrum brings to question whether cancer ST6GAL1 overexpression is beneficial or ultimately detrimental to long-term patient outcomes and highlights the incomplete mechanistic understanding of how ST6GAL1 is involved in cancer progression." (PMID 35676533, 2022). "Thus, the molecules we have identified as ST6GAL1 targets in GBM may mediate ST6GAL1 effects in other cancers as well." (PMID 36345944, 2022). "Importantly, α2,6 sialylation and ST6GAL1 have several known functions in immunomodulation that could be relevant for GBMs or other cancers, especially as immunotherapies become increasingly used and tested." (PMID 36345944, 2022). "Hence, it appears worthwhile to emphasize the sialylation of adhesion proteins in future space research, as the related transition from a two- to a three-dimensional growth appears to mirror some steps of cell migration and cancer cell metastasis in vivo where ST6GAL1 plays a role." (PMID 32143440, 2020). "Furthermore, the correlation between ST6GAL1 levels and worse patient outcomes in a number of other cancers may be in part due to the extrinsic modification of mature tumor-associated leukocytes." (PMID 31408003, 2019). "Consistent with our findings, the omics data identified LAMP1 as a substrate of ST6GAL1, and α-2,6 sialylation of LAMP1 has been previously shown to promote cancer cell invasion and metastasis." (PMID 39937175, 2025). "Intriguingly, Kaplan Meier analysis revealed poorer survival for patients with higher levels of either ST6GAL1, ST3GAL2 and ST8SIA4, similarly to what observed in other cancer models." (PMID 41226744, 2025). "It has been reported that the downstream genes of ZAFS1/miR-150 includes VEGFA, ST6GAL1, ZEB1 and RAB9A in cancer cells [16,]." (PMID 39296014, 2024). "Given the well-known role of ST6GAL1 in promoting cancer initiation and progression, results herein may point to novel avenues for therapeutic intervention by illuminating strategies for preventing or suppressing the overexpression of ST6GAL1 in malignant cells." (PMID 39260693, 2024). "Downregulation of ST6GAL1 decreases Jagged1, DLL-1, Notch1, Hes1, Hey1, MMPs and VEGF, and suppresses cancer cell proliferation, migration and invasion." (PMID 37256139, 2023). "GOLPH3 has been identified as an oncogenic protein in cancer localized to the Golgi, and in a previous study, we found that its interactions with PI4P and sialyltransferases (ST3Gal4 or ST6Gal1) are essential for the regulation of sialylation." (PMID 37451482, 2023). "These analyses indicate that, along with cell and context dependent functions in cancer EMT and metastasis, ST6Gal1-modulated expression of TGF-β has potential roles in immunosuppression." (PMID 36106023, 2022). "Moreover, we present evidence supporting the existence novel but yet uncharacterized cofactors in the exosome-like particles that potently amplify extrinsic ST6GAL1 action, highlighting a previously unknown mechanism linking this enzyme and cancer pathobiology." (PMID 35676533, 2022). "In this respect, overexpression of ST6GAL1 and ST6GALNAC1 has a role in cancer cell stemness, cell survival, metastasis and chemoresistance." (PMID 34070747, 2021). "Furthermore, ST6Gal1 expression is associated with nonmalignant stem and progenitor cells, but also with stemness in cancer and may drive cancer stem cell (CSC)-like characteristics." (PMID 34975914, 2021). "In line with this, knockdown of ST6GAL1 in a osteosarcoma cell line reduced levels of VEGF, suggesting a link between aberrant sialylation and angiogenesis also in this cancer type." (PMID 33921986, 2021).